SALL4 (spalt like transcription factor 4)
Diseases named in the same sentence as SALL4 in open-access papers (continued):
Sharing a sentence is not in itself a finding about the gene and the disease.
liver cancer (19 papers, 2015 to 2025). An epithelial or non-epithelial malignant neoplasm that arises from the liver. "In addition, SALL4 can also be a diagnostic marker for liver cancer." (PMID 35216168, 2022). "To investigate the role of SALL4 in liver cancer development, we first examined Sall4 mRNA expression across diverse murine liver cancer models generated using the SB-HDTVI approach." (PMID 40932240, 2025). "As only a few genes regulating SALL4 have been studied in liver cancer, further research is needed to explore more upstream regulatory genes of SALL4 in this cancer." (PMID 38584262, 2024). "In aggressive liver cancer cells, new target genes that are directly regulated by SALL4 (240 repressed and 190 activated by SALL4) have also been discovered by RNA sequencing analyses." (PMID 38584262, 2024). "In conclusion, we found that SALL4 promoted the progression of hepatic cancer by accelerating the proliferation and invasion and metastasis ability via modulating PTEN, PI3K/AKT signals." (PMID 36575044, 2022). "In contrast, forced expression of SALL4 prominently promotes tumor growth and results in accelerated tumorigenesis in liver cancer, nasopharyngeal carcinoma and cervical cancer." (PMID 32513235, 2020). "SALL4 is suggested as a stem cell marker in liver cancer that regulates the self-renewal of liver cancer cells;7 therefore, we further investigated the effect of miR-497 on self-renewal of HCC cells via tumor spheroid formation assay." (PMID 31650028, 2019). "Regarding 3-year follow-up duration, SALL4 redundancy was negatively related to overall prognosis in both subgroups (Liver cancer: P = 0.02) (Other types: P = 0.01)." (PMID 27007163, 2016). "Among the studies featuring SALL4 expression, the chief source region and cancer type were Japan (n = 5) and liver cancer (n = 9) respectively." (PMID 27007163, 2016). "Although its expression is nearly absent in the adult liver under normal conditions, recent studies suggest that SALL4 may have an unexplored role in liver cancer progression, particularly in specific aggressive HCC subtypes and hybrid HCC–CCA cases." (PMID 40932240, 2025). "This expression pattern in liver cancer with LPC characteristics suggests that SALL4 may be involved in hepatic dedifferentiation and plasticity, potentially influencing tumor development at specific disease stages." (PMID 40932240, 2025). "Given that BMI1 is a validated functional SALL4 downstream effector in diverse malignancies, including liver cancer, we first examined whether Bmi1 expression is elevated in AY-Sall4 liver compared with AY-GFP control livers." (PMID 40932240, 2025). "As a stem cell-associated gene, SALL4 is highly expressed in fetal liver progenitor cells but not in adult hepatocytes and is considered a stem cell biomarker in liver cancers." (PMID 38584262, 2024). "Clusters 1, 2, 3, 5, and 6 represented genes that were highly expressed in stages of embryonic development, but were expressed at low levels in adult livers, including oncofetal genes Afp, Gpc3, Sall4 (cluster 2), H19 (Cluster 3) and Igf2 (Cluster 5), which are re-expressed in liver cancer." (PMID 38225233, 2024). "The C-terminal ZFC of SALL4 is responsible for DNA binding, and SALL4 negatively regulates expression of a family of histone 3 lysine 9-specific demethylases (KDMs) in aggressive liver cancer cells." (PMID 35216168, 2022). "In liver cancer, SALL4 also enhances chemo-resistance by up-regulating ABCG2." (PMID 26935744, 2016). "Furthermore, silencing SALL4 can enhance the chemo-sensitivity of tumor cells to anticancer drugs in liver cancer, endometrial cancer and lung cancer." (PMID 26935744, 2016). "Given the validated SALL4 expression in human CCA, subset of HCC and mixed and/or combined HCC–CCA, we have included following murine liver cancer subtypes in our assessment: murine CCA, HCC, cHCC-CCA, and mHCC/CCA generated by distinct oncogenic drivers." (PMID 40932240, 2025).
liver cancer (continued). "Given the growing clinical interest in YAP1-targeted therapies, understanding how SALL4 and BMI1 interact within the YAP1 signaling pathway may help refine treatment strategies for aggressive liver cancers." (PMID 40932240, 2025). "However, Sall4 expression was undetectable in myrAkt–N1ICD-driven CCA (AN-CCA), KRASG12D-sg-p19-driven CCA (KP19-CCA), β-CatS45D+Met-HCC, and β-CatS45D+Nrf2G31A-HCC, suggesting its context-dependent expression in murine liver cancer subtypes." (PMID 40932240, 2025). "Although SALL4 increases the expression of EMT genes such as TWIST1, the cell migration and invasion of liver cancer cells are not directly affected." (PMID 38584262, 2024).
myelodysplastic syndrome (17 papers, 2012 to 2025). A clonal hematopoietic disorder characterized by dysplasia and ineffective hematopoiesis in one or more of the hematopoietic cell lines. "SALL4 is important for maintaining a pluripotent state in mouse embryonic stem cells, and hypomethylation of the promoter is a common event in myelodysplastic syndrome." (PMID 28616099, 2017). "Similar to Bmi-1, Sall4 expression has been reported in numerous hematological malignancies, including myelodysplastic syndromes, AML, chronic myelogenous leukemia and precursor B cell lymphoblastic lymphoma." (PMID 28122538, 2017). "A recent study demonstrated that the use of demethylating agents such as decitabine and azacytidine can induce the expression of the oncogene SALL4 in patients with myelodysplastic syndrome (MDS), warranting caution in the use of these drugs." (PMID 40558829, 2025). "Aberrant hypomethylation of the SALL4 promoter is described as a common event in AML and myelodysplastic syndrome (MDS)." (PMID 34944911, 2021). "A notable example is SALL4, a known oncogene in hematologic malignancies, which has been observed to become upregulated following HMA treatment in a subset of patients with myelodysplastic syndrome (MDS)." (PMID 41029427, 2025).
colorectal cancer (16 papers, 2013 to 2024). A primary or metastatic malignant neoplasm that affects the colon or rectum. "SALL4 expression in colorectal cancer is reportedly associated with lymph node metastasis and poor prognosis." (PMID 30191347, 2018). "Therefore, SALL4 has been considered a potential diagnostic and prognostic marker of colorectal cancer." (PMID 38584262, 2024). "Reports show that SALL4 promotes colorectal cancer malignancy through different molecular mechanisms." (PMID 36010677, 2022). "Patients with colorectal cancer with coexpression of SALL4 and β-catenin showed advanced lymph node metastasis and TNM stage." (PMID 35216168, 2022). "Another research in colorectal cancer show that miR-508 directly targets SALL4 and modulates its expression." (PMID 31650028, 2019). "The blood copy number of SALL4 in colorectal cancer patients was significantly higher than healthy controls, which was inversely associated with the depth of tumor invasion and the high grade of tumor differentiation." (PMID 26317546, 2015). "Two genes, MACC1 and SALL4, were specifically documented for colorectal cancer." (PMID 39484215, 2024). "High expression of SALL4 is accompanied by worse prognosis in colorectal cancer patients." (PMID 36010677, 2022). "The overexpression of SALL4 was related to a poor prognosis, promoted the invasion and proliferation of colorectal cancer cells, and accelerated the occurrence of EMT, which was characterized by upregulation of Twist, vimentin, and N-cadherin expressions and downregulation of E-cadherin." (PMID 35692499, 2022). "Along with the promising evidence of its role in self-renewal in various cancers, SALL4 may have a role in progression, development and maintenance of colorectal cancers." (PMID 23363002, 2013). "Overexpression of SALL4 mRNA in colorectal cancer may have a role in the progression of the disease and may shed a light in the elucidation of pathophsiology of colorectal cancer." (PMID 23363002, 2013). "SALL4 expression was positively correlated with lymph node metastasis and tumor–node–metastasis (TNM) stages in colorectal cancer, and β-catenin was expressed markedly higher in colorectal cancer than in normal tissue." (PMID 35216168, 2022). "In addition, TRIB3 activated the Wnt-β-catenin signaling pathway via the C-terminal and N-terminal regions of the kinase-like domain in TRIB3, directly binding to β-catenin in colorectal cancer, indicating that activation of Wnt/β-catenin signaling by SALL4 may require TRIB3 expression." (PMID 35216168, 2022). "Murakami and colleagues identified five CAED patients (0.3%) from 1,666 patients with colorectal carcinomas whose clinical pathological features were analyzed followed by IHC staining with enteroblastic lineage markers: glypican-3 (GPC-3), spalt-like transcription factor 4 (SALL4), and AFP." (PMID 37781207, 2023). "SALL4 and GPC3 are also highly expressed in AFP-producing gastric cancers, but there are no reports on their expression in AFP-producing colorectal cancers." (PMID 30191347, 2018).
endometrial cancer (15 papers, 2014 to 2022). Primary or metastatic malignant neoplasm involving the endometrium (mucous membrane that lines the endometrial cavity). "Park found that SALL4 expression was significantly associated with a poor overall survival as compared to SALL4-negative HCCs, and implied poor prognosis in human hepatocellular and endometrial cancers." (PMID 28887597, 2017). "Specifically, SALL4 promotes cell migration, proliferation, drug resistance, and invasion by upregulating c-Myc in endometrial cancer." (PMID 35692499, 2022). "On the other hand, the transcription factor SALL4 is highly activated in various malignant tumors including cervical, liver, lung, gastric, breast, and endometrial cancers." (PMID 33947962, 2021). "High SALL4 expression levels have been correlated with poor overall survival of patients with aggressive tumors such as hepatocellular, endometrial cancer, gastric, and esophageal cancer." (PMID 28321397, 2017). "In endometrial cancer, however, SALL4 promotes tumor chemo-resistance by activating c-myc to regulate MDR1/P-gp." (PMID 26935744, 2016). "It has been shown that SALL4 has functional role(s) in metastasis and drug resistance in aggressive endometrial cancer." (PMID 24860834, 2014). "As evidence, it has been shown that SALL4 is related to Car resistance in endometrial cancer by inducing epithelial-mesenchymal transition (EMT) and MYC expression, whereas reducing SALL4 expression enhances Car efficiency in endometrial cancer cells." (PMID 36362083, 2022). "Sal-like protein 4 (SALL4) is an additional transcription factor whose increased expression promoted metastasis by the EMT process in colorectal, gastric, basal-like breast, and endometrial cancer cells." (PMID 33081056, 2020). "SALL4 is a therapeutic target in intrahepatic cholangiocarcinoma (ICC) and endometrial cancer." (PMID 28887597, 2017).
colon carcinoma (14 papers, 2016 to 2025). "Although SALL4 is rarely mutated (0.1%) in GC, analysis of the TCGA pan-cancer dataset revealed that SALL4 is amplified in GC and other human cancers, including lung squamous cell carcinoma, colon carcinoma, bladder carcinoma, and lung adenocarcinoma." (PMID 33644042, 2021). "But SALL4 transcript levels are low in colon and colon tumours, even after being increased in primary tumours." (PMID 40241172, 2025). "The anti-cancer effects of chrysin on tumor cells in colon cancer included induction of apoptosis and attenuation of the SALL4 expression." (PMID 35610288, 2022). "Intriguingly, SALL1 is downregulated in colon cancer, whereas SALL4 is overexpressed in it." (PMID 40869218, 2025). "However, the overexpression of SALL4 accelerated the invasion and proliferation of colon cancer cells, which was manifested as downregulation of E-cadherin and upregulation of N-cadherin, vimentin, and Twist." (PMID 35692499, 2022). "During the development of colon cancer, miR-219-5p expression decreased, leading to a significant up-regulation of SALL4, which could repress cancer cell apoptosis and enhance drug resistance." (PMID 34573282, 2021). "SALL4 was identified as the main target of miR-219-5p in colon cancer." (PMID 34573282, 2021). "miR-219-5p also targets oncogene Sall4 to suppress colon cancer proliferation and invasion." (PMID 28423675, 2017). "MYC, LEF1, KLF4, SALL4, and IRF4 were the five important TFs involved in the regulation of the immune response in colon cancer." (PMID 34938284, 2021). "Thus, SALL4 and ZNF770 transcription was inversely correlated with 5hmC levels during progression from normal to primary colon cancer to liver metastasis." (PMID 40241172, 2025). "However, whether SALL4 was associated with EMT-related factors and the precise effects on colon cancer cells and their internal mechanisms have not been fully explored." (PMID 35692499, 2022).
esophageal squamous cell carcinoma (12 papers, 2015 to 2023). Esophageal squamous cell carcinoma (ESCC) is a type of esophageal carcinoma (EC) that can affect any part of the esophagus, but is usually located in the upper or middle third. "SALL4 activates Wnt/β‐catenin and TGF‐β/SMAD signaling pathways, uncovering a mechanism underlying EMT in esophageal squamous cell carcinoma and gastric cancer." (PMID 36587397, 2023). "SALL4 is an oncogenic protein reported as re‐expressed in various solid cancers such as breast cancers, endometrial cancers, lung cancers, esophageal squamous cell carcinoma, liver cancers, and glioma." (PMID 36587397, 2023). "Another study found that SALL4 modulated the stemness of esophageal squamous cell carcinoma (ESCC) via the Wnt/β-catenin signaling pathway and epithelial–mesenchymal transition (EMT)." (PMID 35216168, 2022). "The inhibition of SALL4 reduces tumorigenicity involving epithelial-mesenchymal transition via the Wnt/β-catenin pathway in esophageal squamous cell carcinoma." (PMID 30423818, 2018). "For example, in esophageal squamous cell carcinoma, silencing SALL4 has been shown to inhibit EMT by inhibiting the activation of the Wnt/β-catenin pathway, thereby inhibiting the survival, migration, invasion, and drug resistance of cancer cells in vitro, as well as the tumorigenic ability in vivo." (PMID 32908919, 2020). "However, the molecular mechanism of SALL4 promoting esophageal squamous cell carcinoma (ESCC) remains to be elucidated." (PMID 27329034, 2016). "In addition, low level of SALL4 expression was inversely correlated with metastasis of esophageal squamous cell carcinoma cells into the lymph nodes." (PMID 26317546, 2015).
seminoma (12 papers, 2015 to 2026). A radiosensitive malignant germ cell tumor found in the testis (especially undescended), and extragonadal sites (anterior mediastinum and pineal gland). "OCT3/4 and SALL4 are stem cell transcriptional regulators that maintain pluripotency in embryonic stem cells and germ cells, making them highly specific markers for seminoma." (PMID 39723237, 2024). "Furthermore, additional EC and pluripotency genes were upregulated (SOX2, LEFTY1 /2, DNMT3L, SALL4, DPPA5, BCAT1, FZD7, LIN28, ZIC3), while seminoma-associated genes where downregulated (SOX17, TFAP2C, cKIT, PRAME), without changing 5mC-levels." (PMID 26226633, 2015). "Radical orchiectomy was performed, and histopathology combined with immunohistochemistry (PLAP+, CD117+, SALL4+, D2-40+, CKpan-, CD30-) confirmed pure seminoma." (PMID 42292176, 2026). "The typical immunohistochemical markers of seminoma are OCT4 (+), PLAP (+), SALL4 (+), and CD117 (+)." (PMID 35512069, 2022). "Positive staining was demonstrated in seminoma for Nanog (red), OCT4 (brown), and SALL4 (brown); skin for SOX2 (brown); and tonsil for pSTAT3 (brown) and CD44 (brown)." (PMID 29046873, 2017). "Seminomas typically stain positively for placental alkaline phosphatase (PLAP), CD117/c-Kit, OCT3/4, SALL4, vimentin, and D2-40." (PMID 25705542, 2015).
embryonal carcinoma (11 papers, 2012 to 2025). A non-seminomatous malignant germ cell tumor characterized by the presence of large germ cells with abundant cytoplasm resembling epithelial cells, geographic necrosis, high mitotic activity, and pseudoglandular and pseudopapillary structures formation. "Overall, when tumor cells simultaneously express CD30, SOX2, OCT4 and SALL4, the diagnosis of extragonadal embryonal carcinoma is almost certain." (PMID 37138865, 2023). "SALL4 is a highly sensitive marker for primitive germ cell tumors which can also show positivity in embryonal carcinoma, yolk sac tumor, and primitive areas of immature teratoma." (PMID 36140449, 2022). "Another 10% of the tumors were composed of embryonal carcinoma, strongly reactive to SALL4, OCT4, and PLAP, and showing moderate expression of CD30." (PMID 26880963, 2016). "Embryonal carcinoma is strongly and diffusely positive for cytokeratin, PLAP, CD30, SALL4, OCT4, and SOX2." (PMID 36140449, 2022). "Embryonal carcinoma staining is positive for OCT 3/4, CD30, and SALL4." (PMID 38817519, 2024). "A SALL4-positive expression was seen in almost all non-trophoblastic GCT (seminoma, embryonal carcinoma (EC) and YST) and in germ cell neoplasia in situ, and in nearly 80% of choriocarcinomas and 60% of immature teratoma." (PMID 39001344, 2024). "Whereas SALL4 reactivity was strong, there was no reactivity to OCT4, CD30, or PLAP, thereby disproving embryonal carcinoma." (PMID 26880963, 2016).
cervical cancer (10 papers, 2016 to 2024). A primary or metastatic malignant neoplasm involving the cervix. "SALL3 plays a potential tumor suppressor role in cervical cancer, whereas SALL4 is an oncogene in this cancer." (PMID 35216168, 2022). "SALL4 enhanced the proliferative capacity of HeLa and SiHa cervical cancer cells through the positive transcriptional regulation of CTNNB1." (PMID 34944911, 2021). "In addition, in cervical cancer, SALL4 recognizes and binds to the CTNNB1 promoter region as a transcription activator and accelerates the expression of β-catenin to upregulate downstream target genes, including c-Myc and CCND1." (PMID 35216168, 2022). "SALL4 expression increased G1 to the S-phase cell cycle progression in cervical cancer cell lines by a mechanism that involves the increment of β-catenin expression, a necessary cofactor for activating the Wnt/β-catenin signaling pathway involved in cell proliferation." (PMID 34944911, 2021). "SALL4 activates MYC and Cyclin D1 by upregulating the Wnt/β-catenin pathway in cervical cancer cells." (PMID 33947962, 2021). "The present case is a unique cervical cancer, consisting of neuroepithelial components positive for CD99 and synaptophysin, immature / atypical intestinal glands positive for SALL4 and CDX-2, cartilage cells, and rhabdomyosarcoma, resembling sinonasal TCS." (PMID 31684979, 2019).